LGALSL (galectin like)
Description:
Does not bind lactose, and may not bind carbohydrates.
Synonyms: GRP; HSPC159
Tractability: PROTAC: its protein half-life has been measured.
Gene: Protein-coding gene on chromosome 2 (64,453,969 to 64,461,381, forward strand). Ensembl gene ENSG00000119862.
Subcellular location (Human Protein Atlas): Nucleoplasm
Gene Ontology:
Molecular function: protein binding; carbohydrate binding
Genetic constraint (gnomAD): Loss-of-function variants: 13 observed, 19.83 expected, observed/expected ratio (o/e) 0.66, 90% interval 0.43 to 1.04. The upper end of that interval is the gene's LOEUF score, 1.04, which puts it in group 4 of 6, group 1 being the genes least tolerant of losing a copy. Missense variants: 189 observed, 218.8 expected, observed/expected ratio (o/e) 0.86, 90% interval 0.77 to 0.98. Synonymous variants: 86 observed, 79.18 expected, observed/expected ratio (o/e) 1.09, 90% interval 0.91 to 1.3.
Gene-disease validity (ClinGen):
ClinGen rates the evidence that LGALSL causes each of these diseases.
amyotrophic lateral sclerosis (inheritance undetermined): Limited. Amyotrophic lateral sclerosis (ALS) is a neurodegenerative disease characterized by progressive muscular paralysis reflecting degeneration of motor neurons in the primary motor cortex, corticospinal tracts, brainstem and spinal cord.
Homologues: Orthologues: chimpanzee LGALSL (100% identical), macaque LGALSL (99% identical), mouse Lgalsl (99% identical), rat Lgalsl (99% identical), dog LGALSL (98% identical), guinea pig LGALSL (98% identical), rabbit LGALSL (98% identical), pig LGALSL (95% identical), mouse Lgalsl2 (78% identical), tropical clawed frog lgalsl (73% identical), zebrafish lgalsla (51% identical), zebrafish lgalslb (44% identical), and 7 more. Paralogues in human: LGALS9 (34% identical), LGALS4 (34% identical), LGALS9B (33% identical), LGALS9C (33% identical), LGALS8 (32% identical), LGALS12 (25% identical), LGALS3 (25% identical), LGALS1 (22% identical), LGALS7 (21% identical), LGALS7B (21% identical), GRIFIN (19% identical), LGALS2 (16% identical), and 4 more.
Diseases named in the same sentence as LGALSL in open-access papers:
LGALSL is named in the same sentence as 8 diseases in open-access papers, as found by Europe PMC text mining. Sharing a sentence is not in itself a finding about the gene and the disease. The quoted sentences say what the papers report.
gastric cancer (1 paper, 2017). A primary or metastatic malignant neoplasm involving the stomach. "In this study, it is the first time to identify NR1I2 and LGALSL associated with gastric cancer as negative impact factors influencing the prognosis of this cancer." (PMID 29088749, 2017).
LGALSL also shares sentences with these, for which no sentence is quoted: cancer (3 papers); infection (2); breast carcinoma (1); Deep Venous Thrombosis (1); endometriosis (1); Nephropathy (1); tumor (1).